SNORD111 (small nucleolar RNA, C/D box 111)
Synonyms: HBII-82
Gene: Small nucleolar RNA gene on chromosome 16 (70,538,005 to 70,538,098, forward strand). Ensembl gene ENSG00000221066.
Gene Ontology:
Biological process: RNA processing
Cellular component: nucleolus
Homologues: Orthologues: chimpanzee SNORD111 (98% identical), macaque SNORD111 (91% identical), pig SNORD111 (88% identical), rabbit SNORD111 (84% identical), mouse Snord111 (83% identical), rat Snord111 (80% identical). Paralogues in human: SNORD111B (66% identical).
Diseases named in the same sentence as SNORD111 in open-access papers:
SNORD111 is named in the same sentence as 2 diseases in open-access papers, as found by Europe PMC text mining. Sharing a sentence is not in itself a finding about the gene and the disease. The quoted sentences say what the papers report.
breast carcinoma (1 paper, 2025). "We then evaluated the functional significance of loss of Snord67 or Snord111 in breast cancer cells." (PMID 40316533, 2025). "To evaluate the function of these snoRNAs in 4T1 breast cancer cells, we generated Snord67 and Snord111 knockout clones using the CRISPR/Cas9 system." (PMID 40316533, 2025).
tumor (1 paper, 2025). "Notably, we found that the snoRNAs Snord67 and Snord111 were upregulated both in micro-injected LNs and in de novo LN metastases, raising the possibility that the LN microenvironment induces the upregulation of these snoRNAs, perhaps as an adaptive mechanism in tumor cells." (PMID 40316533, 2025). "To determine whether Snord67 and Snord111 expression also increased in de novo LN metastases, we measured expression of these snoRNAs by RT–qPCR in matched pairs of MFP tumor subclones and de novo LN metastasis subclones." (PMID 40316533, 2025).